RAD50 (RAD50 double strand break repair protein)
Diseases named in the same sentence as RAD50 in open-access papers (continued):
Sharing a sentence is not in itself a finding about the gene and the disease.
cancer (continued). "Within the prioritized variants only p.R1093* in RAD50 gene (rs121912628) was reported as pathogenic in ClinVar database (OMIM: 604,040.0001) and in the COSMIC list of variants that have previously been associated with cancer predisposition (COSM1060699)." (PMID 28376765, 2017). "NBN is DNA repair family gene, involved in the MRE11/RAD50/NBN complex, with nine variants (rs1805794, rs1805790, rs36226237, rs924, rs376639, rs1061302, rs1063054, rs2735383, rs805794) described as associated with high cancer risk." (PMID 28402931, 2017). "MRE11A and RAD50 homozygous deletion are each identified in carcinomas." (PMID 26438152, 2015). "Interestingly, all of these genes, except RAD50, are also in the cancer census gene list and it is known that these genes are playing an important role in genomic integrity such as DNA repair pathways." (PMID 24550935, 2014). "However, in 4 from 5 ILC cases we observed rather moderate than strong RAD50 positive staining in the nucleus of cancer cells." (PMID 23181716, 2012). "Therefore, the alterations of the Rad50 foci formation in cells derived from hypersensitive cancer patients observed in the present study cannot be explained by the differences in the cell cycle distribution between the cell strains used." (PMID 15150571, 2004). "In contrast to the hMre11 and Rad51 data, the fraction of Rad50 foci-positive cells (filled symbols) in the irradiated cells from hypersensitive cancer patients (88%) was significantly higher (<0.005) than in control cells (41%) and cells from cancer patients with normal reaction to RT (44%)." (PMID 15150571, 2004). "The expression levels and focal nuclear distribution of DNA repair proteins, hMre11, Rad50 and Rad51 were investigated in skin fibroblasts strains derived from cancer patients with adverse early skin reaction to radiotherapy using Western blot and foci immunofluorescence techniques, respectively." (PMID 15150571, 2004). "Analysis of the immunofluorescence data revealed that cells derived from hypersensitive cancer patients differed markedly in their Rad50 foci forming response to IR from the cells derived from healthy subjects and cells from cancer patients with normal clinical reaction to RT." (PMID 15150571, 2004). "The observed alteration of the distribution of radiation-induced Rad50 foci in cells derived from cancer patients with acute side reactions to radiotherapy might contribute to their radiation therapy outcome." (PMID 15150571, 2004). "Indeed, we found a protracted Rad50 foci formation in irradiated cells derived from cancer patients with increased early reactions to radiotherapy." (PMID 15150571, 2004). "However, the importance of these RAD50 mutations for cancer risk and survival is not well understood and thus more extensive studies are needed." (PMID 35501303, 2022). "The increased level of chromosomal aberrations observed in NbnHZ fibroblasts and tumour cells and in NBS1 and RAD50 hypomorphic mutation carriers suggests that the defective DDR in these individuals is the outcome of Nbn haploinsufficiency and the origin of genetic instability and cancer proneness." (PMID 35839783, 2022). "Thus, we performed multivariate Cox analyses without TMB (with each DDR gene), and identified POLE and RAD50 mutations as independent prognostic indicators regardless of cancer type and MMR status." (PMID 33960179, 2021). "Most notably, racial differences between Black and White samples in the expression of genes pertaining to homology-directed repair, including RAD50, RAD51, MRE11, ERCC1, and BRCA2, were observed in five cancer types." (PMID 37345032, 2023). "On the other hand, MRE11, RAD50 and NBS1 protein components of the MRN complex are often overexpressed and sometimes essential in cancer." (PMID 35839783, 2022). "MRE11, RAD50, and NBS1 expressions as clinical biomarkers for cancer prognosis and responses to chemotherapies have been reported." (PMID 36213114, 2022).
cancer (continued). "The clinical importance of HR for cancer therapy, mainly of MRE11, RAD50, and, NBS, has already been reported." (PMID 36324569, 2022). "The HR pathway is initiated by MRE11, RAD50, and NBS1 a complex termed MRN (Inhibiting homologous recombination for cancer therapy)." (PMID 34199757, 2021). "SAHA inhibited radiation-induced upregulation of RAD50 and RAD51 in diverse types of cancer cells, suggesting a possible role of impaired homologous recombination (HR) repair pathway in SAHA-induced radiosensitization." (PMID 29118323, 2017). "Immunohistochemical analysis of MRE11, RAD50 and NBS1 was successful in a maximum of 134 carcinomas." (PMID 28073364, 2017). "Carcinomas with homozygous deletions in either MRE11A, RAD50, ATRIP or PALB2, 4 genes that are essential for mammalian cell viability, are present in the publically available TCGA database." (PMID 26438152, 2015). "Two SL cancer-related partners of PRDX2, RAD50 and MRE11A are part of MRN protein-complex involved in DNA double-strand break repair, cell-cycle checkpoint activation, telomere maintenance and meiotic recombination." (PMID 20015360, 2009). "In papillary thyroid carcinoma (PTC), the downregulation of MRE11 and RAD50 expression, through the lncRNA SLC26A4-AS1-mediated disruption of the DDX5-E2F1 transcription factor complex, inhibits the invasion and metastasis capability of cancer cells." (PMID 37509263, 2023). "Indeed, it was shown that MSI cancer cells could no longer efficiently repair DSBs in the context of splice-altering mutations in the ATM gene or in the MRE11 gene from the MNR (MRE11/NBS1/RAD50) DNA mutation repair system." (PMID 36833239, 2023). "However, findings in these genes do make cancer patients eligible for clinical treatment trials (NBN, NCT02401347, NCT04171700; RAD50, NCT02401347, NCT02286687)." (PMID 35626031, 2022). "Interestingly, four of the six targetable genes, CDK4, RAD50, CHEK1, and MDM2, were involved in two or more major cancer-related pathways." (PMID 33557149, 2021). "Pathways derived from NOTCH3, PARD3, CACNA1A, MAX, RAD50, FUS and LMO2 were cancer-related." (PMID 34540367, 2021). "C1QBP stabilizes the MRE11 protein by forming an MRC complex with MRE11/RAD50 and inhibiting MRE11 exonuclease activity, thereby demonstrating that C1QBP plays a crucial role in the DNA damage response and serves as a potential target for cancer therapeutics." (PMID 33708767, 2021). "Finally, our data suggests a strategy for the design of novel small molecules that can modulate the activity of Rad50 and interrupt ATM signaling, possibly providing another approach for synthetic lethality in anti-cancer therapies." (PMID 31889185, 2020). "In conclusion, our study has revealed an unanticipated role of tumor suppressor INPP4B in maintenance of genome integrity by facilitating Rad50 mediated DNA double-strand break repair, provided a new therapeutic strategy for INPP4B-based therapy for cancer treatment." (PMID 32341333, 2020). "This suggests that mutations in conserved residues of MRE11 are less tolerated than those of RAD50 or NBS1/NBN, possibly because these mutations are not advantageous to cellular transformation or cancer progression." (PMID 33339169, 2020). "However, it is worth noting that RAD50 is a repair factor that has been identified in the DSB reaction and is highly expressed in many cancers." (PMID 32922536, 2020). "The MRE11/RAD50/NBS1 (MRN) complex plays an essential role in detecting and repairing double-stranded breaks, and thus the potential roles of MRE11, RAD50 and NBS1 proteins in the pathogenesis of various cancers is the subject of investigation." (PMID 30176843, 2018).
cancer (continued). "These include cancer hallmarks of various types: oncogenes (BCL2, BRAF), caspases (CASP6/7), transcription factors (E2F3), cell cycle genes (CDC42, CDK2, CDKN2A), cancer related kinases (JAK2/3, MAPK4/6/14) and DNA repair genes (BRCA1, PARP1 and RAD50)." (PMID 28059167, 2017). "In addition, the cancer genome atlas (TCGA) database was interrogated for alterations in: 1) ATM, MRE11A, RAD50 and NBN; 2) ATR, ATRIP and TOPBP1; and 3) 15 FA genes." (PMID 26438152, 2015). "To date, the association of the molecular variants in the RAD50 and MRE11 gene with the cancer risk has not been so extensively studied." (PMID 24093751, 2013). "We observed moderate (2+) to strong (3+) nuclear RAD50 staining with no cytoplasmic staining apparent in normal and cancer cells in the most cases." (PMID 23181716, 2012). "In our investigation we also showed strong RAD50 nuclear staining of non-cancerous and cancer cells." (PMID 23181716, 2012). "Because both the ATM and MRE11 genes, which as act as players in the MNR (MRE11/NBS1 (Nibrin)/RAD50 (RAD50 double strand break repair protein) DNA damage repair system, participate in double strand breaks (DSB) repair, their frequent splicing alterations in MSI cancers lead to impaired activity." (PMID 36833239, 2023). "However, multivariate Cox regression with TMB, cancer type, and MMR status showed that MMR status, and POLE and RAD50 mutations were no longer independent prognostic indicators, whereas TMB was an independent prognostic indicator." (PMID 33960179, 2021). "However, multivariate Cox regression with TMB, cancer types, and MMR status showed that POLE and RAD50 mutations were not independent prognostic indicators, whereas TMB was an independent prognostic indicator." (PMID 33960179, 2021). "Vorinostat was additionally found to suppress the DNA repair proteins, RAD50 and MRE11, in cancer cells and not normal cells, collectively resulting in cancer cell death." (PMID 40011240, 2025).
tumor (91 papers, 2008 to 2026). "RAD50 has been shown to be involved in the regulation of DNA damage repair and is associated with tumor prognosis." (PMID 40995126, 2025). "MSH-2 low tumors had higher tumor mutational burden (p=0.003) and higher frequency of (frameshift) mutations in the double-strand break repair gene RAD50 (p<0.01)." (PMID 38950928, 2024). "Loss of heterozygosity (LOH) of the pathogenic germline variant was observed in the tumour DNA for 21 of the 22 patients (95.5%) (the single exception was RAD50)." (PMID 37762691, 2023). "On the other hand, low expression of RAD50/BARD1 in ERBB2-low cohort had a significant association with higher tumor stages (p = 0.013)." (PMID 37474724, 2023). "Low nuclear RAD50 [46% (339/733)] was highly associated with high tumour grade, high mitotic index, ER- and high-risk NPI phenotypes (all p values < 0.01)." (PMID 34782604, 2021). "In further cohort of 4904 tumours (cohort 2), low RAD50 mRNA was significantly associated with poor survival in the whole cohort (p = 0.01), ER+ cohort (p = 0.03) but not in ER− cohort (p = 0.91)." (PMID 34782604, 2021). "Like the tumor borne mutations described in this study, those Rad50 alleles also exhibit SOF phenotypes in which Tel1 activation is impaired." (PMID 32187176, 2020). "One XB type tumour (YOPC31) had mutations in the DNA damage pathway (RAD50, RAD51, BLM and BRD7), with the highest mutational burden (6.24 mutations/Mb), but the TIDE score of this tumour indicated lower responsiveness to anti-PD-1/PD-L1 therapy." (PMID 32235905, 2020). "Three rad50 (R1217C, E1235K, and D1241N) and two mre11 alleles (A173V, D370Y), each of which appeared to be heterozygous in their respective tumor, conferred defects in DSB repair when modeled in yeast." (PMID 32187176, 2020). "We found that a significant fraction of tumor-borne RAD50 and MRE11 mutations exhibited separation of function phenotypes wherein Tel1/ATM activation was severely impaired while DNA repair functions were mildly or not affected." (PMID 32187176, 2020). "Low RAD50 expression levels in the tumor periphery (TP) were significantly associated with adjuvant therapy treatment (p = 0.04)." (PMID 29189711, 2017). "Kaplan–Meier survival analysis revealed that very low RAD50 expression in the TC was significantly associated with worse DFS (p = 0.031) and decreased OS (p = 0.044), indicating that the loss of RAD50 expression would possibly increase tumor aggressiveness." (PMID 29189711, 2017). "Kaplan–Meier survival analysis demonstrated that low RAD50 expression in the tumor center (TC) was significantly associated with worse DFS (p = 0.016), whereas the association of RAD50 expression and OS was of borderline significance (p = 0.056)." (PMID 29189711, 2017). "Loss of MRE11 protein was found in 30.7% of EC tumours and significantly associated with loss of RAD50, NBS1 and mismatch repair protein expression." (PMID 24927325, 2014). "MMR-deficient CRC tumours and cell lines frequently tend to accumulate mutations within microsatellite repeats of genes implicated in DSB repair pathway (eg, MRE11 and RAD50), suggesting an enhanced sensitivity of these tumours to camptothecin analogues." (PMID 18941461, 2008). "In accordance with this notion, we observed the acquisition and clonal expansion of a somatic 17q gain in progressive tumor B3 (collected at splenectomy), which was maintained in B4, and subclonal expansion of a clone carrying RAD50 somatic mutation from B3 to B4." (PMID 34001881, 2021). "In summary, our study reveals that tumor borne alleles (rad50-D67N/Y, rad50-R1259C, mre11-E38K, and rad50-L1240F) found in 25 distinct tumors exhibit separation of function phenotypes specifically impairing Tel1 activation, while only partially affecting DSB repair." (PMID 32187176, 2020). "We also identified LOH in the tumor specimen of the patient with the variant c.281T>C (RAD50 gene)." (PMID 33134171, 2020).
tumor (continued). "Furthermore, Ad-RAD50 sensitized NPC cells to IR by causing dramatic tumor regression and inducing apoptosis in vivo." (PMID 26951044, 2016). "Since several studies have shown that neoplasms harboring RAD50, BRCA and RB1 mutations are susceptible to a group of pharmacological inhibitors of the enzyme poly ADP ribose polymerase (PARP), patients whose tumors present these mutations might benefit from personalized targeted therapy." (PMID 37373240, 2023). "We assessed RAD50 expression in tumor tissue by IHC since RAD50 is a core protein of DSB recognition, a starting point of the HRR pathway." (PMID 41332664, 2025). "Case 6, which had the highest number of SNVs, had missense mutations in ATM, POLE and BRCA2, as well as known pathogenic mutations from ClinVar in MSH6, RAD50, APC and NF1, likely explaining the high mutational load in this tumor." (PMID 40670673, 2025). "These tumor biopsies showed upregulation of p-Rad50, a marker of ATM pathway activation, after treatment with ceralasertib, as well as an increase in the number of γH2AX-positive cells." (PMID 37934611, 2024). "In the colony formation experiment, we also observed that specific knockdown of RAD50/RPS3 protein restored the inhibitory effect of Olaparib on tumor cell proliferation." (PMID 37759323, 2023). "Four carriers of germline mutations had additional somatic DDR mutations in the primary tumor: ERCC4; BRCA1, ATM, FANCD2, and MLH1; BRCA1; and BRCA2, RAD50, and ATR." (PMID 36446793, 2022). "MRE11 is the core protein of the RAD50/MRE11/NBS1 complex with a primary role in DNA damage repair, and it has been diversely associated with tumor development including OSCC." (PMID 35629265, 2022). "In our cohort, a comprehensive tumor profile including homologous recombination genes (i.e., ATM, PALB2, RAD50, RAD51, RAD51B, RAD51C, RAD51D...) was performed for 100 cases, finding pathogenic alterations in four tumor samples, as previously reported." (PMID 35406410, 2022). "The authors demonstrated that RAD50 over-expression was correlated with shorter disease-free survival and radioresistance in lung cancer patients who underwent tumor resection followed by post-operative radiation therapy." (PMID 36358724, 2022). "Previous studies targeting RAD50 or the MRN complex combined with cisplatin treatment resulted in tumor cell sensitization." (PMID 34572942, 2021). "Immunostaining of Ki‐67 showed a higher proliferative index in tumours with Rad50 overexpression and a lower proliferative index in tumours with Rad50 knockdown than their corresponding control cells." (PMID 34734468, 2021). "Although rare, we observed a complete loss of MRE11 expression in 14% (90/659) of tumours, complete loss of RAD50 expression in 5% (40/733) of tumours and complete loss of NBS1 expression in 9% (109/1166) of tumours." (PMID 34782604, 2021). "When MRE11, RAD50 and NBS1 were combined, we observed that survival in patients whose tumours had low MRE11/low RAD50/low RAD50 was significantly lower compared to patients whose tumours had high MRE11/high RAD50/high RAD50 expression." (PMID 34782604, 2021). "Four datasets (Rossler Liver 2 14, Guichard Liver 15, Rossler Liver 14, and Chen Liver 16) from the Oncomine database were analysed to validate the differential expression of RAD50 in HCC tumour and normal tissues." (PMID 32922536, 2020). "Four variants showed LOH in the tumor specimen (ATM c.4709T>C; CHEK2 c.1036C>T; PALB2 c.1001A>G, and RAD50 c.281T>C), which is an indication of pathogenicity." (PMID 33134171, 2020). "Yeast RAD50 and MRE11 mutants corresponding to tumor borne alleles were integrated into a diploid yeast strain at their respective chromosomal loci, and haploid spores were derived by tetrad dissection." (PMID 32187176, 2020). "Herein, we modeled twenty-five RAD50 and MRE11 tumor alleles in yeast and in vitro in an attempt to shed light on the tumor suppressive function(s) of the complex." (PMID 32187176, 2020).